TH (tyrosine hydroxylase)
Diseases named in the same sentence as TH in open-access papers (continued):
Sharing a sentence is not in itself a finding about the gene and the disease.
Cognitive impairment (13 papers, 2017 to 2024). Abnormal cognition is characterized by deficits in thinking, reasoning, or remembering. "Therefore, the blockade of A2AR and the upregulation of TH activity and expression likely contribute to caffeine's ability to mitigate cognitive impairment caused by chronic hypobaric hypoxia exposure in mice." (PMID 39670604, 2024). "To conclude, bilateral intrastriatal administration of 6-OHDA can induce cognitive deficit, beside motoric one and substantial reduction in TH levels in the brain, but with incomplete depletion of dopaminergic SN cells." (PMID 36979662, 2023). "This treatment alleviated cognitive deficits, with an increase in tyrosine hydroxylase and vesicular monoamine transporter two and significantly decreased plasma membrane reuptake transporter (DAT)." (PMID 32955434, 2020). "Since the TH-positive neurons significantly decrease in 12-month-old KI mice, it is possible that cognitive impairment may develop in further aged KI mice." (PMID 39130376, 2024). "The present study demonstrates that the Cys-HCl administration induced distinguishable movement disorders, olfactory dysfunction, and signs of cognitive impairment in the experimental mice, accompanied by a marked reduction in dopamine-producing TH-positive cells in both the SN and OB." (PMID 39061373, 2024). "Caffeine exhibits potent neuroprotective effects against chronic high‐altitude‐induced cognitive impairments, potentially through its action on A2AR, leading to enhanced TH expression and subsequent release of dopamine and its related neurotransmitters." (PMID 39670604, 2024). "Three months after 6-OHDA treatment, cognitive deficit was accompanied by decreased AMPAR activity and TH levels (HPC, S), while levels of the proteins involved in insulin signaling remained largely unchanged." (PMID 36979662, 2023). "Interestingly, the cognitive deficits and protein changes in TH and DAT were not dose dependent suggesting a lower threshold for these effects." (PMID 33299021, 2020).
synucleinopathy (13 papers, 2016 to 2025). A neurodegenerative disease that is characterized by the abnormal accumulation of aggregates of alpha-synuclein protein in neurons, nerve fibers or glial cells. "Altogether, our findings implicate that TH participates in αSyn pathology, providing a potential explanation for the selective loss of dopaminergic neurons in synucleinopathies." (PMID 36371400, 2022). "β5i expression and changes in proteasomal structure have been found in tyrosine hydroxylase (TH+) cells in postmortem brains of people with PD-like synucleinopathies such as multiple system atrophy (MSA) and progressive supranuclear palsy (PSP)." (PMID 30128145, 2018). "Changes to TH levels may reflect a combination of both dopaminergic and noradrenergic effects, both of which may induce behavioral deficits in mouse models of synucleinopathy." (PMID 29544548, 2018). "In Lewy body diseases, multimodal biomarker integration—including myocardial 18F-dopamine PET, olfactory testing, and synuclein–tyrosine hydroxylase co-localization—can distinguish synucleinopathy-positive from -negative patients." (PMID 40640892, 2025). "Brain immunohistochemistry for TH-positive (TH+) neurons revealed that CNO treatment in the absence of synucleinopathy (WTLC) had no impact on DA neuronal density in the SNc compared with saline treatment (WTControl)." (PMID 35316276, 2022).
ischemia (11 papers, 2013 to 2024). A hypoperfusion of the BLOOD through an organ or tissue caused by a PATHOLOGIC CONSTRICTION or obstruction of its BLOOD VESSELS, or an absence of BLOOD CIRCULATION. "Levels of tyrosine hydroxylase, the rate-limiting enzyme in DA synthesis, have also been shown to fluctuate post-ischemia, being decreased 9 days after GCI while being upregulated at the 30-day mark." (PMID 35058756, 2021). "We found an increased number of TH positive neuronal fibers in the ischemic territory both following transient and permanent focal ischemia, both in rats and mice similarly." (PMID 34638567, 2021). "Expression or activity of tyrosine hydroxylase in the hippocampus can be enhanced by ischemia or stress." (PMID 32283526, 2020). "Our data show more densely packed TH nerve dots after salidroside treatment, indicative of an elevated TH activity, in combination with a high DA concentration in the early periods after ischemia." (PMID 31920641, 2019). "This may be attributed to the fact that the residual TH-positive neurons release NE to the hippocampus during intestinal ischemia/reperfusion injury." (PMID 35945306, 2022). "In addition, tyrosine hydroxylase (TH) positive neurons were enlarged in sizes following ischemia based on immunostaining signal, particularly in chronic post-MI samples." (PMID 28542617, 2017). "Interestingly, tyrosine hydroxylase is present in endothelial cells in both bovine aortic endothelial cells and mice superficial femoral arteries from hindlimbs, and its expression is increased in both hypoxia and ischemia, respectively." (PMID 28837636, 2017).
paraganglioma (11 papers, 2009 to 2025). A benign or malignant neoplasm arising from paraganglia located along the sympathetic or parasympathetic nerves. "A common aspect of paraganglioma culture is the formation of cell agglomerations or masses that appear initially to include many synaptophysin and tyrosine hydroxylase-positive cells but quickly lose these cells or cells lose expression of these markers." (PMID 36178902, 2022). "Tyrosine hydroxylase was consistently found in the cytoplasm of paraganglioma neoplastic cells and of the endothelia from both tested tissues." (PMID 30199552, 2018). "As expected, the immunohistochemistry for tyrosine hydroxylase was positive in both Crotalus durissus terrificus and Bothrops jararaca brains as well as in the human paraganglioma sample." (PMID 30199552, 2018). "We selected five carotid body paragangliomas and assessed the expression and expected staining pattern of S100, a marker for sustentacular cells and of tyrosine hydroxylase, a marker for chief cells." (PMID 19849834, 2009). "Using the chicken anti-TH monoclonal antibody, TH was found to be moderately to strongly positive in paraganglioma neoplastic cells and endothelia, in cortical neurons from the positive control Crotalus brains (data not shown) and, most importantly, in aortic endothelial cells." (PMID 30199552, 2018). "In preliminary experiments (development/standardization assays), tyrosine hydroxylase was detected in all tested tissues (i.e., in the human paraganglioma and in aorta samples from two Crotalus serpents) using both primary antibodies (that is, the rabbit- and the chicken-raised anti-TH antibodies)." (PMID 30199552, 2018). "A subsequent analysis of induced Phd2 deletion in type I cells (tyrosine hydroxylase (TH) expressing cell lineage) of carotid bodies (tyrosine hydroxylase (TH), TH-IRES-CreER) found a multilineage expansion and features that resembled paragangliomas." (PMID 38509356, 2024). "While calcitonin and CGRP can also be expressed in paragangliomas, the demonstration of tyrosine hydroxylase and GATA3 distinguishes paraganglioma from other neuroendocrine neoplasms." (PMID 32632840, 2020). "Moreover, among neuroendocrine marker-positive and cytokeratin-negative sinonasal neoplasms, the expression of tyrosine hydroxylase favors paraganglioma versus ONB." (PMID 35522392, 2022). "For example, paraganglioma generally expresses GATA3 and tyrosine hydroxylase, while neurocytoma does not." (PMID 35663322, 2022). "In contrast to the PanNETs though, paragangliomas are negative for Keratins (e.g., AE1/AE3 or CAM5.2) or CEA with immunochemistry (as they are non-epithelial neoplasms), whereas they exhibit immunopositivity for GATA-3 and tyrosine hydroxylase (TH)." (PMID 36010170, 2022). "Both paraganglioma and panNETs with paraganglioma-like morphology show S100-positive sustentacular cells complicating the differential diagnosis, which is mainly based on the lack of low weight cytokeratins positivity and GATA3, tyrosine hydroxylase, PHOX2B, and Hand2 expression in the former." (PMID 40668487, 2025).
type 2 diabetes (9 papers, 2020 to 2026). "A SNP (rs10770141) in the human TH gene resulting in reduced expression of TH was associated with lower type 2 diabetes risk, supporting our results." (PMID 33352682, 2020).
dementia (8 papers, 2015 to 2025). Loss of intellectual abilities interfering with an individual's social and occupational functions. "We demonstrate in this report that TH-ir, presumably noradrenergic LC neurons are vulnerable during the onset of dementia as evidenced by their loss in aMCI and AD and the association of this loss with multiple measures of cognitive deterioration and neuropathological accumulation." (PMID 28109312, 2017). "In addition, TH activity of the post-mortem adrenal medulla was assayed in controls, PD, senile dementia and hypertensive encephalopathy." (PMID 35460433, 2022). "ILBD seems to represent a precursor stage to PD; these subjects have no diagnosed movement disorders or dementia, but certain amounts of LB pathology, loss of dopaminergic neurons and reduced levels of TH." (PMID 26834537, 2015).
Hyperglycemia (8 papers, 2010 to 2025). An increased concentration of glucose in the blood. "Our results showed that the ratio of TH and ChAT was imbalanced in hyperglycemia, indicating that both the sympathetic and vagus nerves were impaired during T2DM." (PMID 40380290, 2025). "After 4 weeks of hyperglycemia, retinal tissue displays a decrease in tyrosine hydroxylase (TH) levels, but an increase in the levels of GFAP, NF-κB and IKK, consistent with inflammation." (PMID 39056672, 2024). "Differential changes in GAD and TH levels suggest early sensitivity differences of these transmitter systems and tissues to hyperglycemia, with levels of both proteins displaying significantly increased levels after longer exposure." (PMID 38983568, 2022). "To investigate whether hyperglycemia has any pathological impact on the nigrostriatal dopaminergic system, we examined the expression of dopaminergic neuronal markers, TH and dopamine transporter (DAT), by Western blotting." (PMID 35255986, 2022). "The F1 population showed a mean plasma glucose level that was indistinguishable from B6 strain, suggesting that hyperglycemia is inherited in a recessive manner for the TH alleles." (PMID 21167066, 2010). "Furthermore, consistent with the SN, in the striatum, decreased expression levels of TH and DAT were also observed in the STZ-treated α-syn mice at three months after injection, indicating that the long-term hyperglycemia causes damage to both dopaminergic neurons and terminals in α-syn mice." (PMID 35255986, 2022). "After 8 weeks of hyperglycemia, Rel-A/NF-κB protein levels are still elevated in the zebrafish retina and brain, as are GAD and TH levels, suggesting neuronal differences; decreases in memory are observed after 8 and 12 weeks." (PMID 39056672, 2024). "Extending hyperglycemia to 8 weeks shows continued inflammation in retina as well as increases in both GAD (glutamic acid decarboxylase) and TH levels, suggesting neuronal deficits." (PMID 39056672, 2024). "Surprisingly, the lower levels of GAD and TH at 4-weeks, does not correlate with the observed decrease in b-wave amplitude suggesting more than one effect of hyperglycemia in retina." (PMID 38983568, 2022).
iron deficiency (8 papers, 2016 to 2025). "It's possible that these systems are particularly vulnerable to iron deficiency due to both tyrosine hydroxylase and tryptophan hydroxylase being iron-dependent proteins that are the rate-limiting steps of monoamine neurotransmitter synthesis." (PMID 39239479, 2024). "A study that used iron-deficient anemic mouse models showed that iron deficiency can impair dopamine reuptake because tyrosine hydroxylase, which is iron-dependent, is important for dopamine synthesis." (PMID 38096177, 2023). "Furthermore, chronic microbleeding can lead to iron deficiency, reducing tyrosine hydroxylase activity and thereby impairing 5-HT synthesis and sleep regulation." (PMID 41211279, 2025). "For example, iron acts as a co-factor of tyrosine hydroxylase, which is the rate-limiting enzyme for dopamine synthesis, whereas the D2 receptor is an iron-incorporating protein, and iron deficiency further contributes to the hypo-functionality of D2 receptors." (PMID 36362642, 2022). "Given that tyrosine hydroxylase, an enzyme responsible for dopamine synthesis, is iron-dependent and iron deficiency impairs dopamine reuptake in a mouse model, iron deficiency is a side effect of long-term PPI treatment that is possibly associated with PD development." (PMID 35337125, 2022).
autism (7 papers, 2014 to 2023). Persistent deficits in social interaction and communication and interaction as well as a markedly restricted repertoire of activity and interest as well as repetitive patterns of behavior. "The AHI1-knockout autism mouse model showed low expression of TH and a decrease in dopamine synthesis." (PMID 37200906, 2023). "Down-regulation of the expression of the rate-limiting enzyme in dopamine biosynthesis, tyrosine hydroxylase (TH), in AHI1-knockout (KO) mice is responsible for AHI1-deficiency-mediated autism symptoms." (PMID 37200906, 2023). "Alterations in DA-mediated responses have also been reported in the BTBR mice, a model for idiopathic autism, accompanied by decreased TH expression in several DA innervated brain regions." (PMID 35369647, 2022). "T. gondii parasite can directly affect neurotransmitter levels owing to its tyrosine hydroxylase encoding the gene for dopamine biosynthesis, constituting a probable link to ADHD and autism development." (PMID 35669051, 2022).
breast cancer (7 papers, 2021 to 2025). A primary or metastatic malignant neoplasm involving the breast. "The results indicated that high expression levels of OPN4, NOS2, GPR157, NCOA2, CLOCK, and TH were associated with shorter OS in breast cancer patients, while high expression of EGR3, NR1H3, RELB, SIAH2, and ADRB1 was linked to improved survival rates." (PMID 41031266, 2025). "The repetitive optogenetic activation of the VTA tyrosine hydroxylase (TH) in the medial prefrontal cortex attenuated stress-induced progression of breast cancers and reduced serum concentration of norepinephrine and corticosterone." (PMID 40376000, 2025). "When 50% ethanol extracts of PVL and TH were combined in a 2:1 ratio, the synergistic anti-breast cancer effect was more potent, achieving an IC50 value of 5.54 mg/mL and a combination index (CI) of 0.73." (PMID 39840098, 2024). "Notably, the 50% ethanol extracts of PVL and TH displayed stronger anti-breast cancer effect compared to their water counterparts, with IC50 values of 6.47 mg/mL and 11.68 mg/mL, respectively." (PMID 39840098, 2024). "Similarly, among the 50% ethanol extracts of TH, the extract from Shanxi Province displayed the strongest anti-breast cancer effect, while the extract from Anhui Province was the least effective." (PMID 39840098, 2024). "In order to examine the influence of chronic stress on the local activation state of both sympathetic and parasympathetic nerve systems in the lungs of mice with breast cancer, the expression of TH and VAChT, markers of sympathetic and parasympathetic nervous system respectively, was examined." (PMID 37773152, 2023). "Double immunofluorescence staining with the newly formed neuron-specific marker neurofilament-L (NF-L) and the sympathetic nerve marker tyrosine hydroxylase (TH) revealed that 4T1 mammary tumors displayed denser sympathetic innervation 5, 7, and 9 days after tumor development." (PMID 37847562, 2023). "Chronic stress resulted in marked progression of breast tumors, and repetitive optogenetic activation of VTA TH terminals in the mPFC significantly attenuated stress‐induced progression of breast cancers and reduced serum concentration of norepinephrine and corticosterone." (PMID 33112032, 2021).
Hypoglycemia (7 papers, 2015 to 2024). A decreased concentration of glucose in the blood. "These stress models, which include social defeat, immobilization, foot shock, and hypoglycemia induction, decrease TH phosphorylation in the brain." (PMID 39607552, 2024). "Recent studies have shown that ARC-projecting TH+ catecholamine neurons in the NTS mediate hypoglycemia-induced feeding and that TH+/NPY+ NTS neurons stimulate feeding." (PMID 38246589, 2024). "TH mRNA levels were found to increase within the adrenal gland of non-diabetic rats subjected to seven episodes of both repeated insulin-induced hypoglycaemia and 2DG-induced glucoprivation." (PMID 38392992, 2024). "In our own laboratory, one episode of 2DG-induced glucoprivation and insulin-induced hypoglycaemia increased site-specific TH phosphorylation at Ser31 and Ser40 within the adrenal medulla within one hour." (PMID 38392992, 2024). "A study investigating TH phosphorylation in rats exposed to two episodes of insulin-induced hypoglycaemia per day for two days concluded that reduced catecholamine synthesis was the cause of reduced adrenaline response." (PMID 38392992, 2024). "By contrast, there is undoubtedly another subpopulation of TH+ NTS neurons that is inhibited by hypoglycemia, since some NTS TH neurons have been shown to respond to glucose concentration decreases by reducing their potential firing." (PMID 35055143, 2022). "This study is the first to assess both the short-term and long-term regulation of adrenal TH enzyme activity following prior exposure to insulin-induced hypoglycemia in normal rats." (PMID 25713330, 2015). "In all experimental groups, exposure to acute (RS and 2RS) or recurrent hypoglycemia (RH and 2RH) resulted in gradual increases of the relative rate of TH gene transcription (#P < 0.05)." (PMID 25713330, 2015). "Furthermore, seven episodes of insulin-induced hypoglycaemia also increased TH protein levels within the adrenal gland in rats." (PMID 38392992, 2024). "However, after three episodes of hypoglycaemia, TH immunoreactivity was consistent with basal levels, reportedly due to the inhibitory effects of NPY on TH expression leading to reduced adrenaline response." (PMID 38392992, 2024). "Acute metabolic stress such as insulin-induced hypoglycemia triggers a counterregulatory response during which the release of catecholamines (epinephrine), the activation of tyrosine hydroxylase (TH) enzyme and subsequent compensatory catecholamine biosynthesis occur in the adrenal medulla." (PMID 25713330, 2015). "Additionally, we found that TH protein expression was increased in the adrenal medulla following three episodes of insulin-induced hypoglycaemia, when measured at 60 min after the last episode, suggesting that long-term regulation of catecholamine synthesis is unlikely to be affected in HAAF." (PMID 38392992, 2024). "In untreated diabetic rats, the adrenal medullary TH mRNA level was significantly lower than the normal rats and PNMT mRNA levels were reduced in untreated diabetic rats exposed to two episodes of hypoglycaemia for 4 days." (PMID 38392992, 2024). "This study also clarifies that the reduction in TH immunoreactivity was not due to altered cell proliferation or apoptosis of the chromaffin cells following hypoglycaemia." (PMID 38392992, 2024). "In insulin-treated diabetic rats, adrenal medullary TH protein level was increased after seven episodes of hypoglycaemia despite no increase in TH mRNA levels." (PMID 38392992, 2024). "In contrast to TH mRNA levels, the frequency of recurrent daily hypoglycemia episodes did not significantly affect the magnitude of PNMT mRNA elevation after glucose clamp." (PMID 25713330, 2015).